CD34 (CD34 molecule)
Diseases named in the same sentence as CD34 in open-access papers (continued):
Sharing a sentence is not in itself a finding about the gene and the disease.
meningioma (21 papers, 2012 to 2025). A generally slow growing tumor attached to the dura mater. "CD34 is a useful but less specific marker that is positive in many other tumors, including solitary fibromas and some meningiomas." (PMID 37717004, 2023). "Immunohistochemically, SFTs are in most cases diffusely positive for STAT 6 CD34, while meningiomas are typically reactive for EMA." (PMID 30508695, 2019). "In the CNS, SFTs are usually dura-based, meningioma-like masses and are known to arise from the ubiquitous CD34-positive dendritic interstitial cells of meningeal coverings without meningothelial differentiation." (PMID 26155787, 2015). "However, S100 and CD34 can be expressed by a significant percentage of meningiomas, especially fibrous ones, and, on the other hand, EMA- and PR-positive meningeal SFT/HPCs have been reported." (PMID 35212813, 2022). "Among meningiomas, 5 grade I samples and 3 grade II samples were CD34-positive (4.9%)." (PMID 24252471, 2013). "On the other hand, meningiomas can only react to a limited extent with CD34 and widely express EMA." (PMID 24252471, 2013). "CD34-positive fibroblasts have been discovered on the dural basal layer, subpial interstice, perineurium, and endoneurium of normal nerves, and in the intraparenchymal perivascular connective tissue; thus, there is a tight connection between SFTs and meningiomas." (PMID 40559210, 2025). "Immunohistochemically, SFT are diffusely positive for CD34, while MSFT are weakened, patchy positive for CD34, which make it difficult to tell MSFT apart from meningiomas." (PMID 26155787, 2015). "We found that ALDH1 and CD34 were expressed in most meningeal SFT and HPC in contrast to meningiomas." (PMID 24252471, 2013). "Although the expression of CD34 is a useful adjuvant to distinguish SFT and HPC from meningiomas, only 25% to 30% of meningeal HPC shows CD34 positivity." (PMID 23029385, 2012). "On the other hand, the expression of CD34 can be lost in several SFT/HPCs, especially among those showing malignant features, while may be detected in about 8–23% of all meningiomas." (PMID 35212813, 2022). "This is a distinctive feature of SFT, since the majority of meningiomas either do not stain or exhibit only weak focal immunoreactivity for CD34." (PMID 25114823, 2014). "Glial fibrillary acidic protein, CD99, CD34, S-100 protein, neuron specific enolase, neurofilament, cytokeratin, cytokeratin 19, and Bcl-2 were negative in MA and meningioma area." (PMID 23198201, 2012). "However, meningiomas typically express epithelial membrane antigen (EMA) positively, while CD34 and STAT6 are negative." (PMID 39175476, 2024). "In contrast, meningiomas are EMA positive and CD34 negative." (PMID 22805173, 2012).
prostate carcinoma (21 papers, 2006 to 2025). A carcinoma that arises from epithelial cells of the prostate gland. "This suggested a close association between CD34, an indicator reflecting tumor neovascularization activity, and the differentiation, stage, and prognosis of prostate cancer." (PMID 32962642, 2020). "CD34, a member of the single-pass transmembrane protein family, plays a key role in angiogenesis and serves as a reliable marker associated with the development of prostate hyperplasia or prostate cancer." (PMID 38778357, 2024). "In several studies, resveratrol treatment blocked nuclear translocation of the p65 subunit of NF-κB in myeloid U-937 cells, in TNF-induced prostate cancer PC-3 cells, and in human CD34+ cells." (PMID 39458478, 2024). "Mozhdeh Foroozan and colleagues demonstrated that an elevated expression of the endothelial cell marker CD34 in prostate cancer (PCa) correlates with increased tumor aggressiveness, establishing CD34 as a valuable prognostic indicator." (PMID 38069225, 2023). "The association of neutrophil-lymphocyte ratio (NLR) and CD34 expression level with PSA level, Gleason score, and clinical stage was investigated in patients with prostate cancer." (PMID 32962642, 2020). "The correlation between NLR and CD34 expression was also investigated to provide evidence supporting the use of NLR for predicting the prognosis of prostate cancer patients." (PMID 32962642, 2020). "Tissue specimens from 96 prostate cancer patients were collected for immunohistochemistry and CD34/periodic acid–Schiff double staining." (PMID 29754422, 2018). "In this study, we assessed the levels of prominent prostate cancer markers: CD117, CD133, CXCR4, and CD34, on circulating cells from prostate cancer patients before and after radical prostatectomy." (PMID 25595903, 2015). "In the present study, the rationale for using these particular markers is that immunostaining of CD31 (endothelial cell protein) and CD34 (vascular endothelial cell protein and neo angiogenesis) have been reported to enable accurate assessment of microvessel density in prostate cancer subjects." (PMID 38323039, 2023). "In a prospective study among 572 men diagnosed with prostate cancer in the Health Professionals Follow-Up Study, those with the most irregular and primitive microvessel density as measured by staining CD34 were more likely to have lethal and aggressive prostate cancer." (PMID 20169138, 2010). "In this study an automated pipeline for BV detection and distribution analysis in pathology images for prostate cancer staging is presented using a combination of CD31, CD34 and collagen IV." (PMID 38323039, 2023). "Proposed markers distinguishing prostate cancer from benign tissues include: CD117, CD133, CXCR4, and CD34." (PMID 25595903, 2015). "Similar with our findings, disseminated prostate cancer cells inhibited CD34+ HSC engraftment and competed for HSC niche, whereas non-metastatic transformed prostate epithelial cells did not repress CD34+ HSC engraftment." (PMID 30089913, 2019). "While only CD117 was a prostate cancer marker in our study, this does not mean that the other markers (CD133, CXCR4 and CD34) were not altered by tumor presence." (PMID 25595903, 2015). "PrCSCs obtained directly from prostate cancer patients, prior to expansion in tissue culture, express CD90, CD73, and CD105 in the absence of CD14, CD20, CD34, CD45, and HLA-DR as demonstrated using an optimized flow cytometry assay." (PMID 23362217, 2013). "These primary prostate cancer stromal cells or PrCSCs are FAP-, CD90-, CD105-, and CD73-positive in the absence of CD14, CD20, CD34, CD45, and HLA-DR expression." (PMID 23362217, 2013).
rheumatoid arthritis (21 papers, 2006 to 2026). A chronic, systemic autoimmune disorder characterized by inflammation in the synovial membranes and articular surfaces. "Further studies on larger sample sizes could clarify whether a supplementation of Vitamin D could modify CD34+ levels and inflammatory indices in patients affected by rheumatoid arthritis and therefore contributing to reduce cardiovascular risk in this patients." (PMID 26241902, 2015). "A previous report showed that CD34-positive synovial fibroblasts from OA and rheumatoid arthritis tissues release high levels of inflammatory cytokines." (PMID 35658936, 2022). "In this clinical trial, we performed unmanipulated auto-HSCT from 2007 to 2009; this was based on similar outcomes of efficacy and safety reported in patients with rheumatoid arthritis undergoing unmanipulated and CD34-selected auto-HSCT." (PMID 30670057, 2019). "While some studies suggest a decrease in CD34+ cells in rheumatoid arthritis (RA), other studies demonstrate increased levels, or indeed no change at all in number." (PMID 30042945, 2018). "We previously demonstrated a role for endothelia-expressed CD34 in the maintenance of vessel integrity in a murine model of rheumatoid arthritis." (PMID 21494591, 2011). "Similarly, in the context of rheumatoid arthritis, chronic inflammation was shown to drive differentiation of synovial fibroblasts (CD34− Thy1+) that share many features with IAFs." (PMID 35085231, 2022). "Angiogenesis is a critical driver of rheumatoid arthritis (RA) development, as are endothelial progenitor cells (EPCs), which contain the cell surface markers CD34, CD133 and vascular endothelial growth factor receptor 2 (VEGFR2), which stimulate postnatal vasculogenesis and angiogenic function." (PMID 34440937, 2021). "We therefore undertook a morphologic study to compare the distribution of TCs/CD34+ stromal cells between normal synovium and chronically inflamed synovium from patients with rheumatoid arthritis (RA) by using CD34 immunohistochemistry and CD31/CD34 double immunofluorescence." (PMID 33350073, 2021). "Bone marrow CD34+ cells from rheumatoid arthritis (RA) patients have abnormal capacities to respond to tumor necrosis factor (TNF)-α and to differentiate into fibroblast-like cells producing matrix metalloproteinase (MMP)-1." (PMID 16519794, 2006). "In addition, one pilot randomized study of HSCT in rheumatoid arthritis did not demonstrate superiority of CD34 selection." (PMID 40830237, 2025).
Sepsis (21 papers, 2006 to 2025). Sepsis is defined as life-threatening organ dysfunction caused by a dysregulated host response to infection. "We found that both neutrophil and lymphocyte counts on day 4 in sepsis were negatively associated with the frequency of CD34+ cells on day 1 (p < 0.05)." (PMID 33542693, 2020). "Notably, in one infant (subject 4), a rapid rise and subsequent decline in CD34+ cell count was observed in close temporal association with sepsis." (PMID 41147034, 2025). "Tong Leung et al46 reported lower circulating CD34+ cell levels at the time of sepsis, followed by increased levels one week later." (PMID 41147034, 2025). "In some infants, such as subjects 4 and 8, elevated levels of inflammatory markers (CRP and IL-6) and sepsis coincided with increased circulating CD34+ cell counts." (PMID 41147034, 2025). "The cell percentage ratio diagrams and Uniform Manifold Approximation and Projection (UMAP) revealed that the proportions of CMPs, neutrophils, NK cells, platelets, and Pre-B_cell_CD34- cells were higher for the patients with sepsis than for the controls." (PMID 40909263, 2025). "There were 7 main cell types identified from sepsis samples, including B cells, monocytes, neutrophils, NK cells, platelets, pre-B-cell CD34 and T cells." (PMID 38495196, 2024). "This process is similar to sepsis in terms of pathophysiology; therefore, it is no surprise that some populations of circulating BMSCs (including CD45−/Lin−/CD34+ VSELs) were previously found to be elevated in PB from patients with sepsis." (PMID 35846982, 2022). "In recent years, investigations have been devoted to understanding the significance of circulating CD34+ proangiogenic progenitors (EPCs) in host defense during sepsis-induced vascular injury." (PMID 36611906, 2022). "Results showed that the percentage of PBMCs expressing CD34 in sepsis patients on day 4 was three times higher (0.0505 ± 0.0100%) than that of the healthy control (0.0170 ± 0.0020%) (p < 0.05)." (PMID 33542693, 2020). "We found that HSPCs (CD34+ cells and CD34+CD38+ cells) were migrated to the peripheral blood during sepsis, which is consistent with previous studies." (PMID 33542693, 2020). "CD34+ platelets were significantly decreased in patients with sepsis as compared to controls, for both single and clustered platelets (2.6 + 3.6 and 9.4 + 1.8% CD34+ plts vs. 24.4 + 12.3 and 80.1 + 2.4% His3+ plts, respectively)." (PMID 32165642, 2020). "Based on that, we suggest, that VCAM-1 signaling appears to play a distinct role in CD34+/CD133+-stem cell homing in the course of sepsis." (PMID 29601599, 2018). "In conclusion, we have demonstrated here for the first time that CD34+/CD133+-stem cells in the clinical setting of sepsis exhibit a high expression of VCAM-1 and that this expression is associated with patient survival." (PMID 29601599, 2018). "Our current work does not provide mechanistic insights into the proposed importance of VCAM-1 expression on CD34+/CD133+-stem cells for homing processes in sepsis." (PMID 29601599, 2018). "Both endotoxemia and sepsis increased the frequency and the total cell count of CD34+ CD38− cells in the BM of hu-NSG." (PMID 26272069, 2015). "Additionally, compared to normal samples, SNRPN exhibited reduced expression in Pre-B cells (CD34−) and T cells of sepsis." (PMID 38167131, 2024). "In recent years, the striking significance of CD34+ vascular progenitors in host defense has promoted numerous lines of investigation for the development therapeutic strategies in sepsis-induced vascular injury, mainly based on CD34+ progenitor transplantation or EV delivery." (PMID 36611906, 2022). "We assessed the dynamic changes of CD34+ cells in sepsis patients after admission." (PMID 33542693, 2020). "The increase in sepsis severity might reflect an increasing need for CD34+/CD133+-stem cell-based vascular regeneration facilitated by an improved homing via VCAM-1." (PMID 29601599, 2018).
Sepsis (continued). "Furthermore the increased mobilization of CD34+/CD133+-stem cells in sepsis correlated with survival." (PMID 29601599, 2018). "Our data suggest, that VCAM-1 upregulation on CD34+/CD133+-stem cells could play a crucial role in their homing in the course of sepsis." (PMID 29601599, 2018). "An increase in sepsis severity resulted in both and increase in CD34+/CD133+-stem cells and VCAM-1-expression by those cells, which might reflect an increase in need for vascular repair." (PMID 29601599, 2018). "CLP-induced sepsis increased both the frequency (3.8 ± 1.1 % versus 0.65 ± 0.32 %, P < 0.01) and total cell count (1.5 × 105 ± 0.8 × 105/ml versus 0.3 × 105 ± 0.2 × 105/ml, P < 0.05) of the early CD34+ CD38− HSPCs." (PMID 26272069, 2015). "Hazard ratio for death due to sepsis was 5.47 (p: 0.039) for CD34/CD45 cells more than 310/μl." (PMID 16981997, 2006). "Therefore, the increase of VEGF in sepsis might even have a beneficial impact on sepsis disease course by promoting endothelial regeneration via CD34+/CD133+-stem cell mobilization or stabilization of CD34+/CD133+-stem cell function." (PMID 29601599, 2018). "In our current study the detected an increase in CD34+/CD133+-stem cell numbers in septic patients using flow cytometry indicates, that there seems to be a distinct positive impact of sepsis on CD34+/CD133+-stem cell mobilization, which might reflect the need for vascular repair." (PMID 29601599, 2018). "In this study, we demonstrate that CD34+/CD133+-stem cells, which have been described to be rich in vascular progenitor cells, exhibited a high expression of the adhesion molecule VCAM-1 in septic patients, which revealed a positive association with sepsis mortality." (PMID 29601599, 2018). "However, in patients with sepsis, the prognostic value of CD34+cells remains under debate." (PMID 24826895, 2014). "A second, smaller increase in both CD34+ cells and CRP was observed during a sepsis episode in the second postnatal week." (PMID 41147034, 2025). "Short-term stimulation (24 hours) of CD34+ HSPCs with sepsis plasma resulted in the up-regulation of these genes and an increase in the fraction of S100A8+ cells in the CD34+ population." (PMID 34103408, 2021). "The frequency of circulating CD34+CD38− HSCs was significantly decreased on the days 1 and 7 of sepsis compared to the healthy controls." (PMID 30824730, 2019). "The expression of VCAM-1, ICAM-1, E-selectin and L-selectin by CD34+/CD133+-stem cells was significantly upregulated in septic patients, and correlated with sepsis severity." (PMID 29601599, 2018). "In CLP sepsis, there was a two-fold increase in the frequency of the TLR4-positive CD34+ CD38− cells (55 ± 13.4 % versus 26.1 ± 13.4 %)." (PMID 26272069, 2015). "To unravel the role of the BM microenvironment in the sepsis-induced HSC expansion, we traced the proliferation history of purified hu-CD34+ BM cells after culturing them in vitro with LPS." (PMID 26272069, 2015). "In the murine CLP-sepsis model, we recently reported significant septic PMVEC death (PI+ PMVEC confirmed through double-labeling with CD31, CD34, and G. simplicifolia lectin) as observed by IVVM and confirmed by pulmonary histology." (PMID 26376777, 2015). "Sepsis increased the percentages of both CD34+ CD38− and CD34+ CD38+ with phosphorylated STAT3 and this effect was diminished by DAPT treatment, suggesting partial crosstalk between these two pathways." (PMID 26272069, 2015). "There was also a significant decrease in CD34+ platelets, which is suggestive of platelet activation, although platelet clusters, another sign of platelet activation, was not increased in sepsis patients." (PMID 32165642, 2020). "Another limitation of this study is its cross-sectional design and the subsequent lack of information on CD34+/CD133+-stem cell numbers during the course of sepsis." (PMID 29601599, 2018).
Sepsis (continued). "Within the group of septic patients, numbers of CD34+/CD133+-stem cells in sepsis survivors were increased by 35% compared to non-survivors, however, this difference was not significant." (PMID 29601599, 2018). "In the light of this controversy, our current data revealed slightly higher CD34+/CD133+-stem cell counts in sepsis-surviving patients, however, this difference was not significant." (PMID 29601599, 2018). "Our study now shows, that VCAM-1 expression is also increased specifically on CD34+/CD133+-stem cells during sepsis, which has not been investigated before." (PMID 29601599, 2018). "Yet, CD34+/CD133+-stem cell levels in sepsis-survivors older than 54 years were significantly increased over sepsis-non-survivors." (PMID 29601599, 2018). "Interestingly, in our models, the expression of TLR4 was upregulated on both CD34+ CD38− and CD34+ CD38+ cells and this is in contrast to modulation of those receptors on monocytes from patients with sepsis." (PMID 26272069, 2015). "We found a decreased absolute number of CD34+cells and EPC in patients with sepsis." (PMID 23936333, 2013). "HR for death due to sepsis was 4.49 (pNS, 95%CI: 0.9122.108) for APACHE II more than 20, 2.19 (pNS, 95%CI: 0.50–9.57) for category of critical illness and 5.47 (p: 0.027, 95%C: 1.21–24.65) for CD34/CD45 cells ≥310/μl." (PMID 16981997, 2006). "When excluding these 7 patients in the statistical analysis—since age has a negative effect on vascular progenitor cell numbers—the CD34+/CD133+-stem cells in sepsis-survivors were significantly increased by 76% compared to non-survivors (Mean ± SD: 0,29 ± 0,13% vs. 0,17 ± 0,13%, p = 0,034)." (PMID 29601599, 2018). "However, we could demonstrate a correlation between CD34+/CD133+-stem cell numbers and both VEGF and Ang2 serum levels which suggests a distinct role of these growth factors in CD34+/CD133+-stem cell mobilization in sepsis." (PMID 29601599, 2018). "Furthermore, a significant correlation between SAPS II and the expression of VCAM-1 (r = 0.61, p = 0.01) and E-selectin (r = 0.59, p = 0.02) by CD34+/CD133+-stem cells of sepsis survivors could be detected, but not of non-survivors." (PMID 29601599, 2018). "Importantly, we found a negative correlation between CD34+ on day 1 and WBC and lymphocytes on day 4 from correlation analysis in sepsis patients." (PMID 33542693, 2020).